GPATCH2 (G-patch domain containing 2)
Description:
Enhances the ATPase activity of DHX15 in vitro.
Synonyms: GPATC2; FLJ10252; CT110; PPP1R30; Pfa1
Tractability: PROTAC: ubiquitination databases record sites on it.
Gene: Protein-coding gene on chromosome 1 (217,426,992 to 217,631,090, reverse strand). Ensembl gene ENSG00000092978.
Subcellular location: Nucleus speckle; Nucleus, nucleolus
Subcellular location (Human Protein Atlas): Nuclear speckles
Gene Ontology:
Molecular function: nucleic acid binding
Cellular component: nuclear speck; nucleus; nucleolus
Genetic constraint (gnomAD): Loss-of-function variants: 24 observed, 27.38 expected, observed/expected ratio (o/e) 0.88, 90% interval 0.63 to 1.23. The upper end of that interval is the gene's LOEUF score, 1.23, which puts it in group 5 of 6, group 1 being the genes least tolerant of losing a copy. Missense variants: 352 observed, 380.33 expected, observed/expected ratio (o/e) 0.93, 90% interval 0.85 to 1.01. Synonymous variants: 124 observed, 128.45 expected, observed/expected ratio (o/e) 0.97, 90% interval 0.83 to 1.12.
Homologues: Orthologues: chimpanzee GPATCH2 (99% identical), macaque GPATCH2 (97% identical), dog GPATCH2 (95% identical), rabbit GPATCH2 (93% identical), pig GPATCH2 (92% identical), guinea pig GPATCH2 (90% identical), rat Gpatch2 (85% identical), mouse Gpatch2 (84% identical), tropical clawed frog gpatch2 (70% identical), zebrafish gpatch2 (54% identical). Paralogues in human: GPATCH2L (31% identical).
Diseases named in the same sentence as GPATCH2 in open-access papers:
GPATCH2 is named in the same sentence as 11 diseases in open-access papers, as found by Europe PMC text mining. Sharing a sentence is not in itself a finding about the gene and the disease. The quoted sentences say what the papers report.
breast carcinoma (5 papers, 2014 to 2023). "While we were unable to determine a role for GPATCH2 in the control of Tnf expression, it would be interesting to assess the impact of the loss of GPATCH2 in the context of breast cancer and NF-κB activation, as this may uncover a role for GPATCH2 in vivo." (PMID 36973252, 2023). "GPATCH2 mRNA was shown to be elevated in ~40% of samples in a gene expression analysis of 42 clinical breast cancer specimens." (PMID 36973252, 2023). "G patch domain containing 2 (Gpatch2) was shown to be overexpressed in a great majority of breast cancer cases, probably regulating a broad range of cellular functions." (PMID 25353171, 2014). "GPATCH2 is a proposed cancer-testis antigen, as expression of Gpatch2 mRNA is high in rat and human testis tissue while elevated GPATCH2 mRNA has been noted in human breast cancer samples." (PMID 36973252, 2023). "Interestingly, three DE lncRNAs also potentially cis regulated the G-patch domain-containing 2 (GPATCH2) gene with potential roles in spermatogenesis and tumor growth during breast cancer." (PMID 29510583, 2018).
atherosclerosis (1 paper, 2025). A disease characterized by the build-up of fatty material and calcium deposition in the arterial wall resulting in partial or complete occlusion of the arterial lumen. "For novel atherosclerosis loci, 4 regions overlapped the most frequently across all stages of multi-trait analyses (nearest gene: BNC2, GPATCH2, INSR, JAZF1)." (PMID 40313769, 2025).
inflammatory skin disease (1 paper, 2023). Inflammatory skin disorders covers a broad category that includes many conditions ranging in severity, from mild itching to grave medical health complications These disorders are common in people of all ages and races. "This indicates that GPATCH2 is not essential to regulate Tnf expression in the SM injection model of inflammatory skin disease." (PMID 36973252, 2023).
cancer (2 papers, 2017 to 2023). A tumor composed of atypical neoplastic, often pleomorphic cells that invade other tissues. "GPATCH2, a paralog of GPATCH2L, is upregulated in cancer cells, localizes to the nucleus where it interacts with RNA-processing machinery, and manipulation in culture alters cell proliferation." (PMID 28137300, 2017).
GPATCH2 also shares sentences with these, for which no sentence is quoted: tumor (4 papers); ependymoma (3); Arthritis (1); colorectal cancer (1); infection (1); inflammatory bowel disease (1); neuroblastoma (1).